STEAP2 (STEAP2 metalloreductase)
Diseases named in the same sentence as STEAP2 in open-access papers (continued):
Sharing a sentence is not in itself a finding about the gene and the disease.
non-small cell lung carcinoma (1 paper, 2022). A group of at least three distinct histological types of lung cancer, including non-small cell squamous cell carcinoma, adenocarcinoma, and large cell carcinoma. "Immunohistochemical methods were used to compare the expression of STEAP2 in normal lung and non-small cell lung cancer (NSCLC) tissues." (PMID 35346237, 2022).
Obesity (1 paper, 2018). Accumulation of substantial excess body fat. "Analysis restricted to adipocytes, the main source of circulating miRNAs in obesity, identified 3 mRNAs (CCL2, STEAP2, EN1) as the main target of miR-374a-5p." (PMID 29769661, 2018).
pulmonary fibrosis (1 paper, 2024). Chronic progressive interstitial lung disorder characterized by the replacement of the lung tissue by connective tissue, leading to progressive dyspnea, respiratory failure, or right heart failure. "Firstly, we did not conduct in vivo study to confirm the efficacy of STEAP2 knockdown in alleviating Bleomycin‐induced pulmonary fibrosis." (PMID 38872435, 2024).
squamous cell carcinoma (1 paper, 2022). A carcinoma arising from squamous epithelial cells. "The expression of STEAP2 in highly differentiated squamous cell carcinoma was significantly higher than that in poorly differentiated squamous cell carcinoma." (PMID 35346237, 2022).
tumor (24 papers, 2012 to 2025). "Thus, the restricted expression profile of STEAP2 may minimize the risk of off-tumor, on-target sink tissues and potential toxicities, compared with the gastrointestinal tract, brain, liver, and kidney expression seen with PSMA." (PMID 37966111, 2023). "Rescue experiments further demonstrated that silencing STEAP2 reverses the tumor-suppressive effects induced by METTL3 overexpression, highlighting the METTL3-STEAP2 axis as a therapeutic target in PTC." (PMID 40463874, 2025). "STEAP2 acts as a tumor suppressor by inhibiting the Hedgehog signaling pathway and epithelial-to-mesenchymal transition (EMT), thereby reducing PTC cell proliferation, invasion, and migration." (PMID 40463874, 2025). "Copper levels were found to be significantly decreased in STEAP2 knockdown cells; this substantiates our finding that tumor tissue with elevated STEAP2 levels has higher copper levels compared to non-tumor tissue with lower STEAP2 levels." (PMID 38830975, 2024). "Public HCC datasets demonstrated upregulated STEAP2 expression in HCC and positive association with tumor grade." (PMID 38830975, 2024). "Here, we report that STEAP2 expression was upregulated in HCC tumors compared with paired adjacent non-tumor tissues by RNA sequencing, RT-qPCR, Western blotting, and immunostaining." (PMID 38830975, 2024). "To validate the role of STEAP2 in tumor progression, we overexpressed STEAP2 in Huh7 and SNU398 cells by creating stable overexpression cell lines." (PMID 38830975, 2024). "Through PI3K/AKT/mTOR signaling, STEAP2 downregulation can promote tumor cell proliferation and metastasis." (PMID 38478326, 2024). "More significantly, we identified a novel mechanism that mediates the tumor-promoting activity of STEAP2 in HCC." (PMID 38830975, 2024). "STEAP2 overexpression in tumor tissue was confirmed via RT-qPCR in which all samples were significantly increased in tumor tissue compared to non-tumor tissue." (PMID 38830975, 2024). "Taken together, the results validate STEAP2 as an ideal prostate tumor antigen displaying high, largely homogeneous expression throughout all stages of disease progression, as well as cell surface distal, normal tissue expression confined to the prostate." (PMID 37966111, 2023). "By contrast, the mean tumor size of cells transfected with STEAP2 cDNA was much larger than that in the control group suggesting that increased STEAP2 expression likely promotes tumor growth in vivo." (PMID 36316642, 2022). "Tumor growth status in the subcutaneous xenograft mouse model showed that the STEAP2 reactivation group had slower tumor volume growth rate, smaller tumors, and lower final tumor weight than the NC groups." (PMID 35436987, 2022). "Through cBioPortal, we conducted a preliminary investigation and identified the genetic alteration status of STEAP2 in different tumor samples of TCGA cohorts." (PMID 36060273, 2022). "In the present study, rescue experiments revealed that silencing STEAP2 partially rescued the tumor-suppressive phenotype induced by METTL3 overexpression." (PMID 35436987, 2022). "To analyze STEAP2 expression in various cells and non-tumor tissues, we used TIMER2 for comparison across TCGA cancer types." (PMID 36060273, 2022). "Taken together, these findings strongly suggest that METTL3-mediated STEAP2 m6A modification plays a critical tumor-suppressive role in PTC progression." (PMID 35436987, 2022). "The expression of STEAP2 in tumor tissues was lower than that in normal tissues, indicating a better prognosis." (PMID 36060273, 2022). "Rescue experiments revealed that silencing STEAP2 partially rescued the tumor-suppressive phenotype induced by METTL3 overexpression." (PMID 35436987, 2022). "We found that STEAP1 was upregulated in tumor tissues, while the expression level of STEAP2 was significantly downregulated." (PMID 35346237, 2022).
tumor (continued). "Activation of the ERK pathway by STEAP2 leads to partial stagnation of the g0-G1 cell cycle in cancer cells, increasing proliferation and tumor development." (PMID 35346237, 2022). "The expression profile and localisation of STEAP2 was examined in normal and cancerous prostate specimens and correlation with tumour aggressiveness was evaluated by IHC." (PMID 29674723, 2018). "Further to the in vitro study, STEAP2 expression and localisation were examined in a cohort of 164 PCa tissues; STEAP2 expression was increased in tumour tissue when compared to normal tissue and this significantly correlated with Gleason score." (PMID 29674723, 2018). "To investigate potential mechanisms of the tumor-promoting activity of STEAP2, we performed whole genome RNA sequencing on the SNU398 control versus knockdown cells (triplicates) and used the Deseq algorithm to estimate the differential expression in read counts and their statistical significance." (PMID 38830975, 2024). "We tested CAR-T efficacy in 6 prostate PDX models of varied 1 and 2+ cell surface STEAP2 expression levels by IHC, and in every model, dose-dependent tumor growth inhibition and/or regression, with accompanying IFN-γ release, was achieved without signs of toxicity as assessed by body weight." (PMID 37966111, 2023). "We further verified whether STEAP2 inactivation was involved in the tumor inhibitory activity of METTL3 in PTC." (PMID 35436987, 2022). "These comparisons revealed a clear decrease in tumor size and growth in the STEAP2 shRNA1 and shRNA2-transfected groups when compared to those in the control and a significant increase in both of these parameters in the STEAP2-overexpressing groups." (PMID 36316642, 2022). "The results showed that STEAP1 and STEAP2 expression was correlated with tumor stage." (PMID 35346237, 2022). "Collectively, these data indicate that STEAP2 may exert its tumor-suppressive function by restraining the Hedgehog signaling pathway and EMT." (PMID 35436987, 2022). "Collectively, these observations indicate that STEAP2 could inhibit aggressive tumor phenotypes of PTC cells." (PMID 35436987, 2022). "Furthermore, we focused on STEAP2 and demonstrated that STEAP2 expression was relatively low in tumor tissues compared to normal tissues, implying a favorable prognosis." (PMID 36060273, 2022). "STEAP2 was characterized as a potential tumor suppressor and could inhibit tumor proliferation and metastasis in PTC." (PMID 35436987, 2022). "We further investigated the effects of STEAP2 reactivation on tumor growth and metastasis in vivo." (PMID 35436987, 2022). "However, there are insufficient data to show that STEAP2 mRNA levels are significantly different between tumor and normal tissues." (PMID 35346237, 2022). "Likewise, STEAP2 knockdown enhanced lung metastasis and tumor growth in vivo." (PMID 35436987, 2022). "In this study, we demonstrate that STEAP2 plays a significant role in HCC cell growth, migration, and tumor progression by performing various rigorous in vitro and in vivo assays." (PMID 38830975, 2024). "A very important gene that we identified is the six-transmembrane epithelial antigen of Prostate-2 (STEAP2), known to be over-expressed in aggressive PCa, which corroborates our study as it was identified in a high-grade tumor." (PMID 37218885, 2023). "It is well known that the Hedgehog signaling pathway is significantly associated with tumor proliferation, while EMT plays a crucial role in metastasis, indicating that these two signaling pathways may account for the aggressiveness induced by STEAP2 deficiency in PTC." (PMID 35436987, 2022). "Taken together, these results indicate that METTL3 induces STEAP2 translation in an m6A-dependent manner, subsequently leading to inactivation of the Hedgehog signaling pathway and EMT, and restrains aggressive tumor phenotypes." (PMID 35436987, 2022).
tumor (continued). "The STEAP2-shRNA-infected groups also exhibited smaller mean tumor volume than the MG63-1 control, and IHC evaluations confirmed lower STEAP2 expression in the RNAi group." (PMID 36316642, 2022). "The gene STEAP2 was found to have an average of eight-fold increase in tumor tissue compared to non-tumor tissue in the 9 cases (sup." (PMID 38830975, 2024). "Of note, the AR+ HOXB13–negative GRN in the ARhigh/PSMAlow sample showed robust STEAP1 and STEAP2 expression, suggesting that co–targeting of STEAP and PSMA in AR–positive disease may be an effective strategy to achieve broader tumor cell coverage." (PMID 38645034, 2024). "Encouragingly, our STEAP2 IHC data in tumor samples indicated high homogeneity of the target, as 93% of CRPC, 89% of lymph node metastatic, and 85% of bone metastatic patient samples showed ≥75% of the tumor-expressing membrane STEAP2." (PMID 37966111, 2023). "Finally, we discovered that the 12 IMRGs expression had significant differences, among which SFXN3, TFR2, TMPRSS6, HMOX1, and LCN2 expressions were elevated in the cancer group, and SCARA5, LTF, STEAP2, SLC39A14, CP, ALAS2, and TF were low expressed in the tumor group." (PMID 37361050, 2023). "This is challenging to evaluate in some in vivo studies owing to the lack of viable tumor tissue at the end of study, but in the CTG-2440 and LuCaP 73 models dosed at the 5 × 105 cell sub-efficacious levels, we observed consistent STEAP2 IHC scoring before and after CAR-T dosing." (PMID 37966111, 2023).
cancer (23 papers, 2004 to 2025). A tumor composed of atypical neoplastic, often pleomorphic cells that invade other tissues. "Aberrant expression of six transmembrane epithelial antigen of the prostate 2 (STEAP2) has been functionally associated with cancer progression in many cancers." (PMID 35436987, 2022). "We utilized cBioportal and found that the “amplification” form of STEAP2 mutation was the most common in the majority of cancers, indicating a novel mutation responsible for STEAP2 function loss, which should be investigated in the future." (PMID 36060273, 2022). "High STEAP2 expression was associated with poor OS for cancers of THCA (p = 0.00063) but with favorable progression for GBM + LGG (p = 0.0026), KIRC (p = 0.0002), and SKCM (p = 0.02)." (PMID 36060273, 2022). "As a result, we evaluated the STEAP2 gene as well as molecular aspects of gene expression and genetic mutation in 33 distinct cancers using data from TCGA and CPTAC databases." (PMID 36060273, 2022). "STEAP1 and STEAP2 are highly overexpressed in numerous types of human cancers, such as prostate, bladder, pancreas, ovary, testis, breast, cervix and Ewing sarcoma; however, their physiological roles in normal and cancer cells are not well understood." (PMID 38830975, 2024). "Further, AZD0754 enforced robust, dose-dependent in vivo efficacy in STEAP2-expressing cancer cell line–derived and patient-derived xenograft mouse models, and exhibited encouraging preclinical safety." (PMID 37966111, 2023). "STEAP2–4 are also found overexpressed in many types of cancer cells, suggesting their involvement in cancer initiation or progression." (PMID 37983176, 2023). "It implied that STEAP2 was most positively correlated with STEAP1 in all cancer types as shown in a heatmap." (PMID 35313641, 2022). "We used the Oncomine database to analyze the mRNA expression levels of STEAP1 and STEAP2 in various cancers and corresponding normal tissues." (PMID 35346237, 2022). "To understand the role of human STEAP2 in cancer progression, we focused on the functions of STEAP2 across cancers." (PMID 36060273, 2022). "STEAP1 belongs to a protein family that comprises three metalloreductases, STEAP2–STEAP4, also known as STAMP1–STAMP3 (20, –, 22), which reduce iron(III) and copper(II) and are also associated with cancer progression (23, –, 25)." (PMID 32409586, 2020). "These two cell lines were therefore selected as a model to evaluate the functional role of STEAP2 in the development of aggressive cancer traits." (PMID 29674723, 2018). "In breast and PRAD, STEAP2 has been reported to suppress cancer progression." (PMID 36060273, 2022). "It remains unclear whether STEAP2 plays a role in the development of many cancers via common molecular processes." (PMID 36060273, 2022). "In support of this, its expression often correlates with the expression of STEAP2 in cancers and both proteins co-purify in detergent, suggesting that they could form a functional complex." (PMID 32409586, 2020). "The expression of STEAP1 and STEAP2 is up-regulated in some cancer types, such as prostate, bladder, colon, pancreas, ovary, testis, breast, etc., but their clinical effects for cancer therapy are unclear.Under hypoferric condition, STEAP3 expression was up-regulated to maintain tumor growth." (PMID 29789480, 2018). "We assume that STEAP2 may have opposite functions due to the heterogeneity of different cancers." (PMID 35436987, 2022). "Co-expression and immune infiltration studies revealed further correlations with STEAP2, PIK3B, and epithelial cells, suggestive of TMBIM6 impacting cancer progression in multiple manners." (PMID 41516091, 2025). "The up-regulation of STEAP2 and STEAP3 expression in cancers may foster the transformed phenotype through their ability to promote iron assimilation." (PMID 34988012, 2021). "Interestingly, the expression of STEAP2 and STEAP3 is similar in different types of malignant tumors, with high or medium levels." (PMID 32802887, 2020).
cancer (continued). "Therefore, we envision that it will be of great interest to focus future research endeavors on these putative assemblies of STEAP1 with STEAP2–STEAP4 family members and other unidentified accessory proteins in relevant cancer tissues." (PMID 32409586, 2020). "STEAP2, also known as 6-transmembrane protein of the prostate 1 (STAMP1) is overexpressed in several types of human cancers, namely prostate, bladder, colon, pancreas, ovary, testis, breast, and cervix, but its clinical significance and role in cancer cells is still unclear." (PMID 27755556, 2016).
adenocarcinoma (1 paper, 2022). A common cancer characterized by the presence of malignant glandular cells. "The expression of STEAP2 in lepidic adenocarcinoma (highly differentiated) was significantly higher than that in solid adenocarcinoma and micropapillary adenocarcinoma (poorly differentiated) (P < 0.05)." (PMID 35346237, 2022).
STEAP2 also shares sentences with these, for which no sentence is quoted: benign prostatic hyperplasia (2 papers); bladder cancer (2); glioblastoma (2); thyroid cancer (2); adenosquamous carcinoma (1); anaplastic astrocytoma (1); anaplastic oligodendroglioma (1); anaplastic thyroid carcinoma (1); astrocytoma (1); cervical cancer (1); colorectal adenocarcinoma (1); colorectal cancer (1); head and neck squamous cell carcinoma (1); idiopathic pulmonary fibrosis (1); kidney chromophobe (1); liver cancer (1); lung squamous cell carcinoma (1); malignant melanoma (1); metastatic disease (1); oligodendroglioma (1); osteofibrous dysplasia (1); pancreatic adenocarcinoma (1); paraganglioma (1); pheochromocytoma and (1); skin cutaneous melanoma (1); stomach cancer (1); uterine corpus endometrial carcinoma (1).